ARL2 (ARF like GTPase 2)
Diseases named in the same sentence as ARL2 in open-access papers (continued):
Sharing a sentence is not in itself a finding about the gene and the disease.
colon cancer (4 papers, 2015 to 2022). "Similar to the cell line data, the human colon cancer tissue data also showed that the tumors harboring the K‐RAS‐activating mutation expressed significantly lower levels of ARL2." (PMID 35567502, 2022). "Since ARL2 facilitates RAS activation, we next examined whether an inverse association between K‐RAS activation mutation and ARL2 expression is observed in human colon cancer tissues." (PMID 35567502, 2022). "ARL2 regulates the dynamics of cytological components and is highly expressed in colon cancer tissues." (PMID 35567502, 2022). "ARL2 is expressed at relatively low levels in K‐RAS active colon cancer cells, but its expression is induced in CSCs." (PMID 35567502, 2022). "The induction of ARL2 expression in CSC was observed in a subset of colon cancers, while basal ARL2 expression in BCC was low." (PMID 35567502, 2022). "While ARL2 promotes proliferation in breast and colon cancer, it suppresses proliferation in glioblastoma." (PMID 35567502, 2022). "ARL2 mRNA expression was also significantly higher in colon cancer tissues than in adjacent normal tissues." (PMID 35567502, 2022). "In the current study, we presented evidence that ARL2 can be a potential target for targeting CSC in the treatment of colon cancer." (PMID 35567502, 2022). "ARL2 was reported to cooperate with miR-214 in regulation of the carcinogenesis of colon cancer and CC." (PMID 33817293, 2021). "MiR-214-3p can inhibit the cell viability and development of colon cancer by inhibiting ADP-ribosylation factor-like protein 2 (ARL2) and mitochondrial transcription factor A (TFAM)." (PMID 33628646, 2021). "Here, we report novel roles of ARL2 in the cell nucleus and colon cancer stem cells (CSCs)." (PMID 35567502, 2022). "Based on these findings, we concluded that ARL2 must play an important role in colon cancer." (PMID 35567502, 2022). "Among the five most fatal cancers, colon cancer expressed the highest levels of ARL2 mRNA." (PMID 35567502, 2022). "Through the analysis of public databases of human tissues, we demonstrated that ARL2 may play an important role in human colon cancer tissues and normal tissues and that ARL2 is related to stem cell properties and performs previously unknown nuclear functions." (PMID 35567502, 2022). "To investigate the potential role of ARL2 in DNA DSB repair, we examined whether any of the DNA DSB repair machineries are associated with ARL2 expression in colon cancer tissues." (PMID 35567502, 2022). "We analyzed public databases and observed the nuclear expression of ARL2 in colon cancer tissues." (PMID 35567502, 2022). "In the present study, we investigated an unknown role of ARL2 in the nucleus, especially in the nucleus of human colon cancer stem cells." (PMID 35567502, 2022). "ARL2 could serve as a target of miR-497-5p to affect the osteosarcoma (OS) development, and a downstream gene of miR-214 to mediate colon cancer progression." (PMID 33817293, 2021). "The function of ARL2 in cell proliferation, as shown in previous studies, indicated that ARL2-knockdown may provide a phenocopy of the effect of miR-214 on colon cancer cells." (PMID 25621032, 2015). "In conclusion, the results of the present study revealed that miR-214 suppresses colon cancer cell growth via the suppression of ARL2, and indicated that miR-214 may present a significant potential therapeutic target for colon cancer." (PMID 25621032, 2015). "In conclusion, we hypothesize the following explanation for the regulation mechanism of miR-124 in colon cancer: miR-214 suppresses cell growth and promotes cell apoptosis by targeting ARL2." (PMID 25621032, 2015). "Therefore, in colon cancer cells with higher K‐RAS activity (with higher expression or activation mutation), ARL2 expression may be increased in CSC." (PMID 35567502, 2022).
glioblastoma (2 papers, 2022 to 2025). The most malignant astrocytic tumor (WHO grade IV). "In attempts to identify novel targets for new CSC‐specific therapy, we previously identified ARL2 as a candidate gene for targeting glioblastoma CSC." (PMID 35567502, 2022). "One of these genes was ARL2, which is preferentially required in glioblastoma cell line‐derived CSC compared with conventional bulk‐cultured cells (BCC: cultured in medium supplemented with 10% FBS, surface‐attached, without enrichment of CSCs) of the same cell line." (PMID 35567502, 2022).
osteosarcoma (2 papers, 2021). A usually aggressive malignant bone-forming mesenchymal neoplasm, predominantly affecting adolescents and young adults. "ARL2 was overexpressed in osteosarcoma cells (SAOS-2, HOS, MG-63 and U2OS) compared to hFOB1.19 cells." (PMID 33617480, 2021). "MiR-646 expression was decreased and ARL2 was overexpressed in osteosarcoma cells (SAOS-2, HOS, MG-63 and U2OS) compared to hFOB1.19 cells." (PMID 33617480, 2021). "We demonstrated that circ_0000527 sponges miR-646 expression in osteosarcoma cells and that ARL2 is a target gene of miR-646." (PMID 33617480, 2021). "We demonstrated that circ_0000527 sponges miR-646 in osteosarcoma cells and that ARL2 is a target gene of miR-646." (PMID 33617480, 2021). "It was demonstrated that miR-646 decreases and that ARL2 is overexpressed in osteosarcoma cells (SAOS-2, HOS, MG-63 and U2OS) compared to hFOB1.19 cells." (PMID 33617480, 2021). "The present study suggested that the circ_0000527/miR-646/ARL2 axis may be a potential treatment target for osteosarcoma." (PMID 33617480, 2021). "In summary, this study revealed that circ_0000527 is overexpressed in osteosarcoma cells and specimens and that ectopic expression of circ_0000527 promotes cell growth, cell cycle progression, invasion and the secretion of inflammatory mediators by modulating ARL2." (PMID 33617480, 2021). "Therefore, the circ_0000527/miR-646/ARL2 axis may be a potential treatment target for osteosarcoma." (PMID 33617480, 2021).
bladder tumor (1 paper, 2024). "In bladder tumor cells, miR-195 directly inhibited ARL2 mRNA and protein levels, indicating that miR-195 may function as a tumor suppressor gene." (PMID 38544804, 2024).
blinding (1 paper, 2018). "ADP-ribosylation factor-like 2 (ARL2) has recently been implicated in OS formation through its association with Binder of ARL2 (BART or ARL2BP), a protein linked to inherited blinding disease." (PMID 30446707, 2018).
cardiomyopathy (1 paper, 2017). A disease of the heart muscle or myocardium proper. "Previously, we showed that mitochondrial ARL2 is increased in abundance several fold, though only in the affected tissues (heart and skeletal muscle), in ant1-/- mice, which display muscle wasting and cardiomyopathy." (PMID 28380071, 2017).
endometrial cancer (1 paper, 2022). Primary or metastatic malignant neoplasm involving the endometrium (mucous membrane that lines the endometrial cavity). "In the case of the ADP-ribosylation factor (ARF)/ARF-like protein (ARL) family, it was observed that a high expression of ARL4D, ARL1, ARF1, and SAR1B in endometrial cancer is associated with better prognosis, while a high expression of ARL4C, ARL2, ARL10, ARL16, and ARL14 promotes worse survival." (PMID 35163161, 2022).
ischemic stroke (1 paper, 2025). A stroke disorder caused by obstruction of blood flow to the brain, due to thrombotic (local blood clot formation) or embolic (due to a blood clot or other material traveling from another site) event. "First, while our integrated bioinformatics and machine learning approach strongly identified ARL2 as a common diagnostic biomarker, the precise causal relationship between ARL2 dysregulation and the pathogenesis of sleep disorders (SD) and ischemic stroke (IS) remains to be fully elucidated." (PMID 41245864, 2025).
leukemia (1 paper, 2021). A malignant (clonal) hematologic disorder, involving hematopoietic stem cells and characterized by the presence of primitive or atypical myeloid or lymphoid cells in the bone marrow and the blood. "We previously demonstrated that miR-15a-5p decreased apoptosis induced by DNR and/or cytarabine in leukemia by downregulating three pro-apoptotic target genes—PDCD4, ARL2, and BTG2—validating the implication of miR-15a-5p in drug resistance." (PMID 34068078, 2021).
lymphoma (1 paper, 2022). A malignant (clonal) proliferation of B- lymphocytes or T- lymphocytes which involves the lymph nodes, bone marrow and/or extranodal sites. "Active replication was also found in other lymphoma samples (CTCL1, NK/TL2, PTBL1, DLBCL3, and ARL2)." (PMID 35740565, 2022).
metastatic cancers (1 paper, 2021). A carcinoma which has spread from the original site of growth to another anatomic site. "Moreover, ARL2, FCGR2A, and KLHDC8B were positively associated with advanced, metastatic cancers compared to healthy controls." (PMID 33955587, 2021).
sleep disorder (1 paper, 2025). A change from the patient's baseline sleeping pattern, in the hours slept and/or an alteration/dysfunction in the stages of sleep. "Through this strategy, we identified ARL2 as a novel circulating biomarker for the detection of the comorbidity of SD and IS, which gives our study a significant clinical advantage for non-invasive, rapid screening, identification of people at high risk for sleep disorders, and prevention of stroke." (PMID 41245864, 2025). "The consistent upregulation of ARL2 in the blood of patients with stroke, sleep disorder, and most notably in those with both conditions, strongly corroborates our pre-clinical findings and underscores the translational relevance of ARL2 as a peripheral biomarker." (PMID 41245864, 2025). "Group 2 (sleep disorder): ARL2 gene expression was significantly higher than the normal group." (PMID 41245864, 2025).
Stroke (1 paper, 2025). Sudden impairment of blood flow to a part of the brain due to occlusion or rupture of an artery to the brain. "This study provides insights into the common molecular mechanisms of SD and stroke, highlighting the potential of ARL2 as a diagnostic marker and therapeutic target." (PMID 41245864, 2025). "Nevertheless, our data identify circulating ARL2 as a promising and readily measurable biomarker that could facilitate risk stratification and early detection of stroke, especially among individuals with pre-existing sleep disturbances." (PMID 41245864, 2025). "Further functional studies are needed to validate the specific role of the ARL2 gene in SD and stroke and to explore its functional mechanisms in disease progression." (PMID 41245864, 2025). "Most importantly, the expression level of ARL2 in the SD + Stroke group exhibited the most pronounced increase, showing statistically significant differences compared to all other three groups (all p < 0.001)." (PMID 41245864, 2025). "QRT-PCR analysis revealed that the relative expression levels of ARL2 were significantly up-regulated in the Stroke group and the SD group compared to the Control group (p = 0.0000198 and p = 0.00121, respectively)." (PMID 41245864, 2025).
tumor (12 papers, 2009 to 2025). "In preclinical models, reduced Arl2 content is associated with enhanced tumor aggressivity while increased Arl2 content is associated with reduced aggressivity and enhanced spontaneous necrosis." (PMID 19829707, 2009). "This treatment effectively modulated Arl2 gene expression in tumors and was associated with increased tumor growth." (PMID 19829707, 2009). "A rt-PCR analysis of fresh human tumor breast samples suggested that low Arl2 expression was associated with larger tumor size and greater risk of lymph node involvement at diagnosis." (PMID 19829707, 2009). "PVT1 knockdown exerted tumor suppressor role in CC progression via the miR-503/ARL2 axis, at least in part." (PMID 33817293, 2021). "It remains to be established which are the key regulators involved in Arl2/PP2A regulation of tumor aggressivity." (PMID 19829707, 2009). "Then the expression of PVT1, miR-503, and ARL2 was examined in the resected tumor tissues." (PMID 33817293, 2021). "While this observation does not allow us to conclude a direct role of TBCC it suggests a possible involvement of TBCC in tumor aggressivity whether through microtubules or through other unidentified pathways such as interaction with the Arl2 protein." (PMID 20384997, 2010). "To determine whether PP2A activity was significantly different according to Arl2 status during tumor growth in vivo, we measured PP2A activity in tumors." (PMID 19829707, 2009). "We observed that modifications of Arl2 expression levels could induce modifications of contact inhibition, clonogenic potential, and tumor growth, including spontaneous apoptosis of tumor cells." (PMID 19829707, 2009). "Both siRNA against Arl2 and against PP2A were found to enhance tumor growth in comparison to controls injected with scrambled siRNA." (PMID 19829707, 2009). "Expression levels of Arl2 and PP2A of tumor and liver samples in mice exposed to control siRNA, anti PP2A siRNA or anti Arl2 siRNA." (PMID 19829707, 2009). "Notably, we observed that ARL2 expression in the IDC core microenvironment (domain 0) was significantly lower than in healthy tissue microenvironments (domains 10 and 12) and the tumor–stroma interface (domain 11)." (PMID 41275376, 2025). "In TCGA, a decreased ARL2 expression could be observed in all subtypes (Proneural, Mesenchymal, Neural and Classical) of GBM, compared to non-tumor samples (P < 0.05)." (PMID 29843637, 2018). "We assessed the effect of Arl2 and PP2A inhibition in vivo on the tumor growth of MDA-MB 231 cells." (PMID 19829707, 2009).
cancer (6 papers, 2009 to 2024). A tumor composed of atypical neoplastic, often pleomorphic cells that invade other tissues. "The strong positive association between most RAD51 family genes in human cancers indicates the potential role of ARL2 in HRR." (PMID 35567502, 2022). "The loss of ARL2 selectively eliminated the cancer stem cell (CSC) population." (PMID 35567502, 2022). "To investigate the role of ARL2 in cancer and cancer stem cells, we attempted to select the most relevant cancer tissues based on clinical data available in public databases." (PMID 35567502, 2022). "These roles, especially those in RAS activation and centrosome assembly, suggest a positive function of ARL2 in cancer or carcinogenesis." (PMID 35567502, 2022). "Recently, ARL2 has been identified as a prognostic and therapeutic target in a variety range of malignant tumors." (PMID 29843637, 2018). "Therefore, we next examined the expression of ARL2 in several cancer cell lines under bulk‐cultured cells (BCC) conditions or CSC‐enriched cultured conditions." (PMID 35567502, 2022). "Furthermore, using orthotopic mouse models, depletion of ARL2 was shown to impair cancer progression." (PMID 32426352, 2020). "However, the function role of ARL2 in cancer is still controversial." (PMID 29843637, 2018). "In recent years, interesting roles of ARL2 (both positive and negative) have been identified in cancer." (PMID 35567502, 2022).
brain disorder (1 paper, 2024). A disease affecting the brain or part of the brain. "Although Arl2 variants have not been found in brain disorders, recent studies identified Arl2 as a candidate gene for an eye disorder and its role in early photoreceptor development via its microtubule functions." (PMID 39137170, 2024).
eye disorder (1 paper, 2024). A non-neoplastic or neoplastic disorder that affects the eye. "Variants in human ARL2 and ARL2BP have been identified in eye disorders, namely, MRCS (microcornea, rod-cone dystrophy, cataract, and posterior staphyloma) syndrome and retinitis pigmentosa, respectively." (PMID 39137170, 2024).
ARL2 also shares sentences with these, for which no sentence is quoted: acute myeloid leukaemia (1 paper); adenocarcinoma (1); Alzheimer disease (1); atrial fibrillation (1); breast adenocarcinoma (1); Cerebral ischemia (1); clear cell renal cell carcinoma (1); Hearing impairment (1); infection (1); liver cancer (1); malignant glioma (1); metastatic tumor (1); MRCS syndrome (1); neurological diseases (1); pancreatic cancer (1); prostate carcinoma (1); retinitis pigmentosa (1); Senile plaques (1).